AHR (aryl hydrocarbon receptor)
Diseases named in the same sentence as AHR in open-access papers (continued):
Sharing a sentence is not in itself a finding about the gene and the disease.
Insulin resistance (continued). "Based on these data, we then hypothesized that GDNP treatment leads to altering the composition of exosomes, and increased exosomal miR-375 plays a predominant role in reversing HFD-Exo mediated development of hepatocyte insulin resistance by decreasing AhR-mediated signaling in hepatocytes." (PMID 33754048, 2021). "Thus, the strong correlations between PCB126 and both AhR bioactivity and ATP concentration imply that exposure to PCB126 may be a major cause of mitochondrial dysfunction in the PIVUS cohort, leading to insulin resistance or cardiovascular defects." (PMID 28839207, 2017). "In addition, drug-induced overexpression of human AHR in mice induces the activation of FGF21 which may then result in decreased insulin resistance." (PMID 27858116, 2017). "Other AhR agonists, such as indoles, have been shown to effectively stimulate the secretion of glucagon-like peptide-1 (GLP-1), thus improving insulin resistance and alleviate symptoms of T2D." (PMID 39944639, 2025). "Conversely, AhR negatively regulates GLUT4 expression, impairing glucose uptake and potentially promoting insulin resistance." (PMID 41440753, 2025). "AhR negatively regulates GLUT4 expression, leading to impaired glucose uptake and potential insulin resistance." (PMID 41440753, 2025). "For example, experimental periodontitis was shown to lead to AHR inactivation in serum, feces and proximal small intestine of C57BL/6N mice accompanied by accelerated body weight gain, increased fat mass, and insulin resistance." (PMID 40687891, 2025). "Inflammation, renin-angiotensin system-sympathetic nervous system activation and insulin resistance, endothelial dysfunction Shared genes among hypertension, NAFLD, fibrosis, and inflammation include LEP, ADIPOQ, AHR and TGFB1." (PMID 37664266, 2023). "Separately, it has been reported that HFD-induced exosome-derived phosphatidylcholine binds to and activates AhR, to inhibit the insulin signaling pathway and induce HFD-mediated insulin resistance." (PMID 36499198, 2022). "Recently, we reported that the serum levels of dioxin-like compounds, aryl hydrocarbon receptor (AhR) ligands (AhRL), and mitochondria-inhibiting substances (MIS) were higher in subjects with T2D or insulin resistance than in normal subjects." (PMID 36358481, 2022). "In our study, the correlation analysis revealed notable relevance of both elevated AHR (r = 0.6188, ***P < 0.0001, Pearson analysis) and RORC (r = 0.2541, *P = 0.0289, Pearson analysis) (relative to GAPDH) mRNA expression to increased insulin resistance." (PMID 32849564, 2020). "Collectively, this suggests that metabolic reprogramming resulting in reduced acetyl-CoA levels following persistent AhR activation by TCDD may have a role in the etiology of cancer and metabolic diseases such as insulin resistance and diabetes." (PMID 36914879, 2023). "Epidemiological studies demonstrate that AhR activation by persistent organic pollutants (POPs) promotes insulin resistance, although the mechanisms are not well understood." (PMID 37443781, 2023). "Aryl Hydrocarbon Receptor Nuclear Translocator/ hypoxia-inducible factor 1 beta (ARNT/ HIF1β), a member of bHLH-PAS family of transcriptional factors, plays a critical role in metabolic homeostasis, insulin resistance and glucose intolerance." (PMID 28005939, 2016). "However, it has also been shown that lack of AhR improved insulin sensitivity and glucose tolerance by increasing energy expenditure and ameliorating high-fat diet-induced insulin resistance in mice." (PMID 39944639, 2025). "Similar to fast-induced adipose factor-KO mice, AHR-KO mice gain weight as expected but do not develop insulin resistance, suggesting that AHR could be the upstream link between microbiota-mediated signals and the host." (PMID 27858116, 2017).
Insulin resistance (continued). "Furthermore, in a recent study, HFD promoted the activation of aryl hydrocarbon receptor (AhR) by exosome-derived PCs, resulting in the repressed expression of insulin receptor substrate 2 (IRS2) and its downstream genes PI3K and AKT, leading to insulin resistance." (PMID 38706565, 2024). "In contrast to those of wild-type C57BL/6 mice, the OGTT and ITT of AhR−/−mice were indistinguishable after treatment with different doses of BPA, suggesting that BPA-mediated insulin resistance depends on the activation of AhR." (PMID 38200540, 2024). "We found that low-dose TCDD-treated AhR-knockdown cells also showed suppressed insulin-induced glucose uptake and Ca2+ efflux, suggesting that the TCDD-mediated insulin resistance is also independent of AhR." (PMID 36358481, 2022). "An interesting point to note is that although MODY-2 shares similarities with the AhR-null mice phenotype of pregnant mice, MODY-2 mice develop mild hyperglycemia under fasting conditions and glucose intolerance, but do not develop insulin resistance, unlike AhR-null mice." (PMID 36418969, 2022).
atherosclerosis (51 papers, 2007 to 2026). A disease characterized by the build-up of fatty material and calcium deposition in the arterial wall resulting in partial or complete occlusion of the arterial lumen. "In Mtb-infected macrophages, an activated AhR pathway can induce the secretion of IL-1β, an important inflammatory cytokine associated with atherosclerosis." (PMID 40508196, 2025). "In the cardiovascular system, AhR promotes vascular and myocardial development, and is closely linked to myocardial hypertrophy, atherosclerosis, myocardial ischemia-reperfusion injury, and hypertension." (PMID 38883986, 2024). "In some diseases associated with atherosclerosis, AhR can serve as a transmitter of an oxidative stress signal." (PMID 35743162, 2022). "Given that AhR signaling has a crucial role in cardiovascular physiology, disturbances in its function have been linked with several cardiovascular diseases, e.g., atherosclerosis and ischemic heart disease." (PMID 35987825, 2022). "For example, in ApoE-KO mice, increased AhR is linked to increased symptoms of atherosclerosis, but on the other hand, activation of AhR through indoles has modulatory effects on the reduction of CVD." (PMID 33401401, 2021). "The current review presented the association between the AhR and inflammation, oxidative stress, lipid infiltration and atherosclerosis." (PMID 31638212, 2019). "Recent studies have revealed that the development of atherosclerosis is closely associated with AhR function." (PMID 31638212, 2019). "Atherosclerosis induced by PAHs has similarly been linked to AhR-dependent effects on cholesterol synthesis." (PMID 31439044, 2019). "Numerous studies have shown that environment pollutants associated with AhR signaling are important factors in atherosclerosis." (PMID 29984241, 2018). "Further, a single nucleotide polymorphism (SNP) that is 5′ of the AHR gene and is associated with variation in AHR expression has been associated with atherosclerosis." (PMID 30513921, 2018). "In certain atherosclerosis-associated diseases, the AhR may serve a role as an oxidative stress signal transmitter." (PMID 31638212, 2019). "Recent studies revealed that AhR may be associated with atherosclerosis-associated diseases, including coronary artery disease (CAD), ischemic stroke and type 2 diabetes mellitus (T2DM)." (PMID 31638212, 2019). "There are three hypotheses underlying the AhR signaling pathways that mediate inflammation and promote atherosclerosis." (PMID 31638212, 2019). "Additionally, the role of the AhR in atherosclerosis and atherosclerosis-associated diseases is reviewed." (PMID 31638212, 2019). "It was suggested that endothelial senescence in atherosclerosis is linked to AhR activation." (PMID 29984241, 2018). "Overall, it seems reasonable to conjecture that suppressed immune responses and increased atherosclerosis risk in uremic patients may be partially caused by increased activity of AHR and accumulated kynurenine." (PMID 28811533, 2017). "Given the role of AHR in mediating inflammation and atherosclerosis, we postulated that TCF21 may alter the risk of atherosclerosis by modulating the AHR pathway." (PMID 28481916, 2017). "Data are accumulating regarding the participation of KP metabolites and AhR signaling in inflammatory processes in vascular and cardiac tissues associated with the initiation of such pathological conditions as coronary heart disease, myocardial infarction, and atherosclerosis." (PMID 39000041, 2024). "However, the roles of the AhR in the pathological development of atherosclerosis and atherosclerosis-associated diseases remain unclear." (PMID 31638212, 2019). "IAA alleviates atherosclerosis by activating the Aryl hydrocarbon receptor (AhR) and inhibiting the TGF-β/Smad pathway." (PMID 40356907, 2025).
atherosclerosis (continued). "Subsequently, this process further activates AhR in macrophages to produce ROS, exacerbating vascular inflammation, promoting lipid accumulation within blood vessels, and ultimately leading to atherosclerosis within the vasculature." (PMID 38883986, 2024). "In this regard, one should realize that the molecular events connected with the participation of KP metabolites and AhR signaling in the development of atherosclerosis and its outcome depend on a cellular context." (PMID 39000041, 2024). "It has been found that the AhR activated by metabolites of the KP takes part in such an inflammatory disorder (key for CVDs) as atherosclerosis." (PMID 39000041, 2024). "It is known that AhR factor has a major role in many vascular diseases, such as atherosclerosis, hypertension, and hyperlipidemia." (PMID 36757399, 2023). "AHR is overexpressed in human atherosclerosis vessels and is known to mediate oxidative stress and inflammation in atherosclerosis." (PMID 37627520, 2023). "The aryl hydrocarbon receptor (AHR) is a ligand-activated transcription factor that is closely associated with inflammation, oxidative stress, lipid infiltration, and atherosclerosis." (PMID 36466649, 2022). "Benzo[a]pyrene (BaP) causes atherosclerosis by activating the aromatic hydrocarbon receptor (AHR) signaling pathway to trigger lipid peroxidation and inflammation, thereby promoting the development of atherosclerosis." (PMID 35276933, 2022). "Collectively, data regarding AhR in atherosclerosis show that AhR activation has both beneficial and adverse effects depending on the different circumstances." (PMID 33401401, 2021). "The aryl hydrocarbon receptor (AhR), an important ligand‐activated transcription factor, has been reported to accelerate atherosclerosis through triggering vascular inflammation and promoting foam cell formation." (PMID 34388961, 2021). "Studies highlight that the expression of AhR is related to atherosclerosis, but the effects of AhR activation is dependent on the agonists, species, and cell type." (PMID 33401401, 2021). "Dietary flavonoids have biochemical anticancer mechanisms by making the aryl hydrocarbon receptor (AhR) the target site and similarly in Alzheimer's disease (AD) and atherosclerosis and chemoprevention and disease therapy." (PMID 32831803, 2020). "Together the current findings indicate that PKA and C/EBP are important components of an alternative AHR pathway in the regulation of inflammatory markers which are critically involved in chronic inflammatory diseases such as atherosclerosis." (PMID 33167400, 2020). "The role of the AhR receptor in the cardiovascular system, particularly the mechanism of action of AhR in atherosclerosis, is discussed in the present review." (PMID 31638212, 2019). "In a murine model that compared high and low affinity AHR, atherosclerosis further increased with low affinity AHR." (PMID 30513921, 2018). "Expression quantitative trait loci (eQTLs)—SNPs that are associated with variation in gene expression—have been identified for AHR and have been associated with important phenotypes, such as MDD, atherosclerosis, and coffee consumption." (PMID 30513921, 2018). "We further show that oxidized LDL, a well-known driver of atherosclerosis in the plaque can activate the AHR pathway." (PMID 28481916, 2017). "A number of other pathways were identified (P <0.001) including IL17a, DC and NK crosstalk, LPS/IL-1 mediated inhibition of RXR function, leukocyte extravasation signaling, atherosclerosis signaling, and aryl hydrocarbon receptor signaling." (PMID 26503507, 2015). "The main pathways involved include the focal adhesion‐PI3K‐Akt‐mTOR‐signaling pathway; AhR; fluid shear stress and atherosclerosis; protein processing in endoplasmic reticulum; thermogenesis; adipogenesis; and several inflammatory‐related pathways (IL‐5, IL‐2, TGF‐β receptor, and IL‐6 signaling)." (PMID 41169019, 2025).
atherosclerosis (continued). "AhR has been shown to contribute to inflammation regulation in atherosclerosis." (PMID 39000041, 2024). "AhR activity is regulated and triggered by endogenous ligands, which include oxidized low-density lipoproteins and Trp metabolites, which accumulate in atherosclerotic plaques and affect atherosclerosis progression." (PMID 39000041, 2024). "The potential biological pathways affected by tetrachloroethylene are AHR pathway, apoptosis, estrogen signaling, ferroptosis, fluid shear stress & atherosclerosis, lipid and atherosclerosis, miRNA in DNA damage, nuclear receptors meta-pathway, and oxidative stress response." (PMID 38982523, 2024). "The molecular pathways potentially affected by the investigated hydrocarbons include aryl hydrocarbon receptor, chemical carcinogenesis, ferroptosis, fluid shear stress and atherosclerosis, interleukin 17 signaling pathway, lipid and atherosclerosis, NRF2 pathway, and oxidative stress response." (PMID 38982523, 2024). "In addition, the study found that oxidized LDL, a widely recognized contributor to atherosclerosis within plaques, can induce the AHR pathway." (PMID 38250610, 2024). "Sustained TCDD-induced AHR activation usually results in rapid protein ubiquitination that targets the receptor for degradation by the proteasome, leading to toxic results such as cell cycle arrest, chloracne or increased atherosclerosis." (PMID 37179416, 2023). "It should be said that the division of the pathological involvement of AhR in the development of atherosclerosis into three hypotheses is largely arbitrary." (PMID 35743162, 2022). "Studying the AHR pathway could provide additional molecular biological evidence on the mechanism of BaP-induced atherosclerosis, especially during LDL deposition and oxidation." (PMID 35276933, 2022). "Kynurenic acid, another endogenous ligand of AhR, promoted the occurrence of atherosclerosis by activating the receptor, and thereby could be used as a risk biomarker for the prognosis of atherosclerosis and plaque stability." (PMID 35721725, 2022). "There are three hypotheses based on the AhR signaling pathways that mediate inflammation and promote atherosclerosis." (PMID 35743162, 2022). "AhR is connected with other signaling pathways, including Wnt and E2 cascades, and further research is needed to clarify the function of AhR and identify new endogenous ligands in order to elucidate the role, regulation, and possible usefulness of AhR in the treatment of atherosclerosis." (PMID 35743162, 2022). "We observed such a change in the immune status of the patients who suffered from atherosclerosis after the treatment with drugs based on EchA, whichis why it seemed to us to be of interest to start examining the capability of EchA to interact with the AhR." (PMID 32429179, 2020). "There is no clinically relevant research on AhR gene polymorphisms and atherosclerosis, to the best of our knowledge, and few studies on AhR gene polymorphism and CAD." (PMID 31638212, 2019). "Furthermore, PAHs accelerate development of atherosclerosis, induce major changes in gene expression depending on AhR, and B[a]P DNA adducts are found in atherosclerotic lesions." (PMID 31439044, 2019). "The identification of novel endogenous ligands and the application of AhR knockout mice may clarify the role, regulation and intervention of the AhR in the treatment of atherosclerosis." (PMID 31638212, 2019). "Exposure to B[a]P, induced atherosclerosis to a greater extent in mice with high-affinity AhR (B6) and had a huge impact on gene expression of the aorta when compared to mice with low affinity AhR (B6.D2)." (PMID 31439044, 2019). "ROS also play an important role in AhR-related atherosclerosis." (PMID 29984241, 2018). "Intercellular adhesion molecule-1 and matrix metalloproteinases, both regulated by AhR, may play a role in atherosclerosis; however, the mechanism remains to be determined." (PMID 29984241, 2018).